RNU6-857P (RNA, U6 small nuclear 857, pseudogene)
Gene: Small nuclear RNA gene on chromosome 18 (30,984,106 to 30,984,215, forward strand). Ensembl gene ENSG00000251702.
Homologues: Orthologues: chimpanzee U6 (98% identical), macaque U6 (92% identical), guinea pig U6 (75% identical), pig U6 (68% identical). Paralogues in human: RNU6-30P (78% identical), RNU6-116P (77% identical), RNU6-378P (77% identical), RNU6-1 (76% identical), RNU6-115P (76% identical), RNU6-11P (76% identical), RNU6-1251P (76% identical), RNU6-144P (76% identical), RNU6-15P (76% identical), RNU6-16P (76% identical), RNU6-2 (76% identical), RNU6-33P (76% identical), and 1286 more.